IFNG (interferon gamma)
Diseases named in the same sentence as IFNG in open-access papers (continued):
Sharing a sentence is not in itself a finding about the gene and the disease.
tuberculosis (continued). "Mechanisms of protection against tuberculosis have not been defined, but defects in IFNγ signalling are strongly predictive of disease so it is likely that the T-cell response plays an important part in protection." (PMID 22243970, 2012). "This study aimed to assess performance of interferon-gamma release assay (IGRA) in diagnosis of active tuberculosis (ATB) with pulmonary and extrapulmonary involvements, and to determine the diagnostic role of IGRA (T-SPOT.TB) and tuberculin skin test (TST) in BCG-vaccinated population." (PMID 22427859, 2012). "This study was conducted to evaluate the performance of a whole-blood interferon-gamma release assay in inpatients who were admitted to the emergency department (ED) with pulmonary infiltrates who required a differential diagnosis with pulmonary tuberculosis (TB)." (PMID 21513568, 2011). "IFNγ plays an important part in immunity to tuberculosis (TB), but although it is necessary, it is not on its own sufficient for protection against TB." (PMID 19941997, 2010). "We show here that the relationship between mycobacterial antigen induced IFNγ and CXCL9 may play a role in determining disease severity in tuberculosis." (PMID 19340290, 2009). "Strikingly, we found a significant trend to increase incidence of tuberculosis with increasing levels of CFP-10-induced IFNγ, but not with CFP." (PMID 20011589, 2009). "The blood based interferon-gamma release assays (IGRA) for the diagnosis of tuberculosis do not discriminate between active TB disease and latent TB infection (LTBI)." (PMID 19065267, 2008). "A tuberculin skin test or an interferon gamma release test can help confirm sensitization to the Mycobacterium tuberculosis bacillus, but these tests are often falsely negative in the case of severe tuberculosis or immunosuppressed patients." (PMID 40722791, 2025). "Interferon-gamma release assays (IGRAs), such as the QuantiFERON®-TB Gold Plus (QFT; Qiagen, Hilden, Germany), are widely used in tuberculosis (TB) screening, especially in children requiring immunosuppressive therapy." (PMID 40821343, 2025). "Bovine tuberculosis (TB) in water buffalo (Bubalus bubalis) is primarily diagnosed using intra vitam tests, as the intradermal tuberculin test (IDT) and the interferon-gamma release assay (IGRA), both of which detect cell-mediated immunity (CMI)." (PMID 41311486, 2025). "Risk factors for M. tuberculosis infection (positive tuberculin skin test (TST) / interferon-gamma release assay (IGRA) and/or TB diagnosis) among contacts were identified using multivariable logistic regression and classification tree." (PMID 41040068, 2025). "The negative interferon-gamma release assay argued against tuberculosis." (PMID 39135827, 2024). "The IGRA assay used in this study was the QuantiFERON-TB Gold In-Tube assay (QFTGIT), a whole blood-based ELISA assay that evaluates IFNγ secretion in response to M. tuberculosis peptides (ESAT-6, CFP10, and TB7.7)." (PMID 38994354, 2024). "HHC—household contact; IGRA—interferon-gamma release assay; IQR—interquartile range; PTB—pulmonary tuberculosis; TB—tuberculosis; TPT—tuberculosis preventive treatment." (PMID 38251204, 2023). "The two commercially available interferon-gamma release assays, T-SPOT.TB (T-SPOT) and QuantiFERON-TB, have been proven to be useful to accurately detect Mycobacterium tuberculosis (Mtb) infection." (PMID 35807065, 2022). "Since macaque monkeys are highly susceptible to tuberculosis, it is desirable for users to take epidemic prevention measures such as confirming that the animals are not affected by tuberculosis with chest X-ray examinations and/or interferon gamma release tests." (PMID 36566381, 2022). "Latent tuberculosis infection (LTBI) screening includes previous TB history, chest radiograph findings, and tuberculin test (TST) and/or interferon-gamma release assays (IGRAs) results." (PMID 33999988, 2021).
tuberculosis (continued). "A preventive prophylaxis policy has been introduced to prevent the M. tuberculosis infected population, as determined by the tuberculin skin test (TST) or an interferon gamma release assay (IGRA), from progressing to active TB." (PMID 31160610, 2019). "The central dogma suggests that within TB lesions, infected macrophages are activated by antigen-specific CD4+ T cells that secrete interferon-gamma (IFN-γ), restricting the growth and dissemination of Mycobacterium tuberculosis (Mtb)." (PMID 31825836, 2019). "Methods currently used to diagnose tuberculosis in wildlife include bacterial cultures and for some species cell-mediated immune (CMI) response assays such as the intradermal tuberculin test (IDT) and interferon gamma (IFN-γ) assays (Maas, Michel & Rutten 2013)." (PMID 31714142, 2019). "However, co-stimulation with IL-7 induced increased proportions IFNγ-producing T cells solely in the study group of healthy contacts (p = 0.003), but not in tuberculosis patients (p = 0.94)." (PMID 28582466, 2017). "The management of household contacts of tuberculosis patients has been complicated by the current worldwide shortage of tuberculin and the expense, technical complexity and lack of availability of commercial interferon-gamma release assays." (PMID 28479622, 2017). "Interferon-gamma (IFN-γ) release assays (IGRAs), such as T-SPOT.TB, QuantiFERON-TB Gold Test (QFT-GT), are more specific and are based on the T cell mediated IFN-γ release after stimulation with specific Mycobacterium tuberculosis (M.TB) antigens." (PMID 27887611, 2016). "Thus, careful and continuous monitoring for development of tuberculosis is absolutely needed even for patients with a negative tuberculosis skin test or interferon gamma releasing assay result on initial evaluation." (PMID 27101309, 2016). "We developed a protocol for detecting antigen-induced expression of the cytokine genes IFNG and IL2 in peripheral blood T cells stimulated ex vivo with M. tuberculosis purified protein derivative (PPD), a standard reagent used for recall responses in tuberculosis." (PMID 26658491, 2015). "We compared two interferon gamma release assays (IGRAs), QuantiFERON-TB Gold In-Tube (QFT-GIT) and T-SPOT.TB, for diagnosis of latent tuberculosis infection (LTBI) in patients before and while receiving tumor necrosis factor (TNF)-α antagonist therapy." (PMID 26474294, 2015). "Although M. tuberculosis antigen-specific interferon-gamma (IFN-γ) release assays can determine whether individuals have been infected with M. tuberculosis, they cannot distinguish individuals with active tuberculosis and those latently infected with M. tuberculosis." (PMID 25703554, 2015). "Preliminary testing for infectious causes included an extensive workup including blood cultures, Fungitell, tuberculin skin (PPD) testing, bronchoalveolar lavage with culture, and interferon gamma release assay (Quantiferon) test for tuberculosis that was all negative." (PMID 25478256, 2014). "Interestingly, recent studies support the IL-17-CXCL13 pathway rather than the IFNγ pathway as a new strategy to improve mucosal vaccines against tuberculosis." (PMID 24489729, 2014). "Data on the performance of interferon-gamma release assays (IGRAs), QuantiFERON TB Gold In-tube (QFNGIT) and T-Spot.TB, in diagnosing tuberculosis (TB) are limited in Southeast Asia." (PMID 25121513, 2014). "However, it has been shown that IFNγ alone does not correlate with protection, but IFNγ remains an important component of the overall immune response required to combat infection with tuberculosis." (PMID 24710359, 2012). "In a murine model of tuberculosis, NK cells were found to be recruited to the lung and to produce IFNγ and perforin, although the absence of an infection phenotype following antibody-mediated depletion led the investigators to conclude that their functional role was redundant." (PMID 22788220, 2012).
tuberculosis (continued). "Interferon gamma (IFN-γ) release assays, such as QuantiFERON®-TB Gold test (QFT-G) and QuantiFERON®-TB Gold In-Tube test (QFT-GIT) are designed to detect M. tuberculosis (Mtb) infection." (PMID 21687702, 2011). "We conclude that DHA reduces the ability of J774A.1 cells to control M. tuberculosis in response to activation by IFNγ, by modulation of IFNγ receptor signaling and function, suggesting that n-3 PUFA-enriched diets may have a detrimental effect on host immunity to tuberculosis." (PMID 20526363, 2010). "IGRAs are T-cell-based assays relying on the principle that sensitised T-cells from a whole blood sample produce the cytokine Interferon-gamma (IFN-γ) when incubated with antigens specific for M.tuberculosis (ESAT-6, CFP-10, TB-Antigen 7.7)." (PMID 19156218, 2009). "Tuberculosis infection screening with either tuberculin skin test or interferon-gamma release assay (IGRA) is not routinely performed among organ donors because of low TB incidence in Québec organ donors." (PMID 39664235, 2024). "Among HHCs who were not already diagnosed with current active TB disease by the TB program, Mycobacterium tuberculosis infection was determined by interferon-gamma release assay (IGRA)." (PMID 36930628, 2023). "Whole blood samples from a total of 20 active TB patients, 83 HD patients, and 52 healthy individuals were collected, and the QFT-GIT test was used for measuring Mycobacterium tuberculosis (MTB)-specific interferon gamma (IFN-γ) level." (PMID 36611380, 2022). "Latent tuberculosis (LTB) does not have any of the clinical symptoms of active tuberculosis (ATB): it is defined by the presence of an immunological reaction to Mycobacterium tuberculosis (Mtb) antigens as determined by a tuberculin skin test (TST) or an interferon-gamma release assay (IGRA)." (PMID 35056035, 2022). "Furthermore, although TPT is given commonly to IFNγ release assay-positive and tuberculin skin test-positive individuals, and individuals with known household exposure to a tuberculosis patient, the vast majority do not progress to tuberculosis disease if left untreated." (PMID 33508224, 2021). "The T-SPOT.TB test, which is one of the interferon-gamma releasing assays for tuberculosis was negative." (PMID 33974187, 2021). "However, tuberculosis antigen-specific interferon-gamma release assay came back negative." (PMID 33827514, 2021). "Interferon-gamma release assays (IGRAs) include the tuberculosis infection-specific cellular immune response (QuantiFERON-TB, QFT) and tuberculosis-infected T-cell spot test (T-SPOT.TB)." (PMID 32256565, 2020). "Tuberculosis interferon gamma release assays and TB Polymerase chain reaction (PCR) were also negative." (PMID 32234012, 2020). "Immunologic tests such as the tuberculin skin test (TST) and interferon gamma (IFN-γ) release assays (IGRAs) can facilitate screening for M. tuberculosis infection, including both latent infection (i.e., LTBI) and infection manifesting as disease (i.e., TB)." (PMID 28545136, 2017). "The interferon-gamma release assay (IGRA) is more specific than the tuberculin skin test to discriminate between tuberculosis (TB) and nontuberculous mycobacterial (NTM) diseases." (PMID 27887611, 2016). "For example, the tuberculin skin tests and interferon-gamma release assays may be useful for diagnosing tuberculosis in non-endemic area, but the use of these tests are limited and cannot differentiate between the latent tuberculous infection and disease in endemic area such as Thailand." (PMID 26511718, 2015). "Recently, the interferon gamma release assay (IGRA), a T-cell based assay using M. tb-specific antigens, has been increasingly used and studied for the diagnosis of both active or latent tuberculosis (TB) infections." (PMID 25020161, 2014). "paratuberculosis (MAP) have shown that a small proportion of the infected animals were misclassified as TB reactors when using the IFNγ test, but not with the SICTT." (PMID 24308747, 2013).
tuberculosis (continued). "Latent TB infection (LTBI) is defined by a positive M. tuberculosis-specific immune response in the PPD or an interferon-gamma release assays (IGRAs) in the absence of active TB." (PMID 23691377, 2013). "Interferon gamma (IFN-γ) release assays (IGRAs), such as the QuantiFERON-TB Gold test (QFT-G) and QuantiFERON-TB Gold In-Tube test (QFT-GIT) are being used as substitutes for the tuberculin skin test (TST) to detect M. tuberculosis (Mtb) infection with increasing frequency." (PMID 21687702, 2011). "The TbD1 region, which is absent in "modern" M. tuberculosis and present in M. africanum and M. bovis, does not induce a discriminatory IFNγ T cell response in TB patients in the Gambia." (PMID 20085647, 2010). "Leucocyte activating chemokines such as CCL2, CCL3, and CXCL8 together with proinflammatory IFNγ, TNFα and downmodulatory IL10 play a central role in the restriction of M. tuberculosis infections, but is unclear whether these markers are indicative of tuberculosis disease severity." (PMID 20041183, 2009). "We therefore decided to develop an assay based on two rounds of in vitro restimulation, to determine IFNγ production in response to M. tuberculosis latency-associated antigens in LTBI, TB patients, and tuberculin skin test (TST)-negative donors." (PMID 19440342, 2009). "This is not surprising as, although IFNγ may be a key cytokine in activation of macrophages for mycobacterial stasis and killing, disease severity outcomes in tuberculosis depend on the balance among several different cytokines in situ, depending on the disease site." (PMID 19274101, 2009). "They measure the T-cell IFNγ production after 16 to 24h of contact with M. tuberculosis specific antigens coded by the region of deletion 1 or RD1 (ESAT-6 + CFP-10 for T-SPOT-TB, and ESAT-6 + CFP-10 + Tb7.7 for QF-TB-IT)." (PMID 19343092, 2008). "Tuberculosis screening revealed a 5 mm PPD induration, negative interferon-gamma release assay and negative PCR and cultures for acid-fast bacilli in sputum and gastric fluid samples." (PMID 41044616, 2025). "Therefore, the development of a new vaccine with an acceptable safety profile that prevents pulmonary tuberculosis and could be administered regardless of HIV status and interferon-gamma release assay (IGRA) status would be a notable advance in the global effort to end the tuberculosis epidemic." (PMID 40614747, 2025). "The interferon gamma release assay (T-SPOT®) was positive, suggesting latent tuberculosis, although there were no signs of active tuberculosis." (PMID 38090401, 2023). "Interferon-gamma release assays (IGRA) overcome this problem by detecting M. tuberculosis complex-specific responses, but studies to determine risk factors for IGRA-positivity in high TB burden settings are lacking." (PMID 36972254, 2023). "Interestingly, we had a negative result for the TB-specific interferon-gamma release assay performed as an auxiliary diagnosis for active Mycobacterium tuberculosis infection." (PMID 33827514, 2021). "P3 had a history of treated tuberculosis many years earlier and was the only non-IRD patient to exhibit higher production of IFNγ than IL-10." (PMID 18442415, 2008). "The whole blood interferon-gamma assay (QuantiFERON-TB-2G; QFT) has not been fully evaluated as a baseline tuberculosis screening test in Japanese healthcare students commencing clinical contact." (PMID 17726533, 2007). "This is particularly confusing since the angiographic pattern is similar in both classic SC and presumed Tuberculosis-SLC and the labs/imaging are often negative except for positive interferon-gamma (IFN-γ) release assay or tuberculin skin test results in the latter entity." (PMID 37589912, 2023).
tuberculosis (continued). "Similarly, in one study, interferon-gamma release assays such as quantiferon TB gold showed a negative result in 28.8% of patients with extrapulmonary tuberculosis, with sensitivity further being affected by HIV status, diabetes mellitus, neutropenia, immunosuppression, and severe TB disease." (PMID 36277529, 2022). "We analyzed frequencies of antigen-specific CD4 and CD8 T cells expressing IFNγ, IL-2, TNF and/or IL-17 from adolescents or adults, with or without Mycobacterium tuberculosis (M. tb) infection, who received MVA85A, AERAS-402, H1:IC31, H56:IC31, M72/AS01E, ID93+GLA-SE or BCG." (PMID 30830940, 2019). "In an attempt to characterize the effect of miR-29a expression we compared IFNγ expression in children with tuberculosis and LTBI as well as expression of both (miR-29a and predicted target IFNγ) in lymphocytes of individual donors but detected no dependency between these factors." (PMID 23613882, 2013). "Additionally, tuberculosis-specific interferon-gamma release assay (T-SPOT), cytomegalovirus (CMV) antigen, β-D-glucan, SARS-CoV-2 PCR, and Mycobacterium avium complex (MAC) antibody tests were all negative, excluding tuberculosis, CMV infection, fungal infections, and COVID-19." (PMID 39759671, 2024). "In this study, we investigated IFNγ responses to M. tuberculosis antigens in the pulmonary immune-compartment and peripheral blood of HIV-infected individuals suspected of having active TB, with initial sputum smears negative for acid fast bacilli (AFB)." (PMID 22778764, 2012). "Additionally, the tuberculin skin test (TST) and interferon-gamma release assays (IGRAs) have been widely utilized for latent tuberculosis infection (LTBI) detection in clinical practice, but neither of these effectively distinguish LTBI from active TB." (PMID 36844400, 2023).